CCNE2 (cyclin E2)
Diseases named in the same sentence as CCNE2 in open-access papers (continued):
Sharing a sentence is not in itself a finding about the gene and the disease.
tumor (106 papers, 2007 to 2026). "The specific targeting of mRNAs encoding for the cell cycle regulators cyclin D2 (CCND2) and cyclin E2 (CCNE2) by expression of adeno-associated virus mediated by miR-26a resulted in considerable tumor reduction in a mouse model of HCC." (PMID 36071981, 2022). "High expression of CCRGs was significantly associated with tumor pathological grade (p<0.05), indicating that a higher grade accompanied higher expression of CCRGs, except for the CCNE2 gene." (PMID 33403032, 2021). "Although both E cyclins have been associated with mechanisms of tumor progression, only the CCNE2 gene has been reported to be preferentially amplified in different types of breast tumors." (PMID 25596745, 2015). "The in vitro and in vivo assays showed that overexpression of miR-26a resulted in cell cycle arrest, inhibited cell proliferation, and decreased tumor growth, which was associated with cyclin E2 downregulation." (PMID 24116110, 2013). "Additionally, CCNE2 is a pivotal cell cycle protein and has been implicated in abnormal activities in numerous tumors, influencing tumor proliferation and oncogenesis." (PMID 39925738, 2025). "In addition, K84Q elevated the mRNA levels of cyclin E2 (CCNE2), a classic gene associated with tumor cell growth." (PMID 39513918, 2024). "Lactylation at the K348 site of cyclin E2 (CCNE2) serves as a critical regulatory node, promoting the growth of tumor cells." (PMID 40589733, 2025). "Specifically, SIRT3 removes lactylation from cyclin E2 (CCNE2) at K348, promoting apoptosis and suppressing tumor cell proliferation." (PMID 41152975, 2025). "hsa-miR-30d-5p, identified as a broad-spectrum candidate for diagnostic and therapeutic studies, regulates cellular functions through downstream targets like PI3K/AKT and cyclin E2 (CCNE2), and its dysregulation is linked to tumor development." (PMID 40034306, 2025). "Upregulation of CCNE2 expression is found in a variety of cancers and correlated with tumor progression." (PMID 39572025, 2024). "CCNE2 is located at chr 8q22.1, the region known to be recurrently altered in HCC and associated with high tumor grade and microvascular invasion." (PMID 38981878, 2024). "Next, we confirmed the positive linear correlations between the mRNA expression of MKI67 vs. CCNA2, CCNB1, CCNB2, and CCNE2, suggesting their role in tumor progression." (PMID 36151566, 2022). "For instance, the CNV of cell cycle-related CCNE2 gene in the groups of Tumor, stage I, and stage III-IV was statistically correlated with the gene expression." (PMID 34238242, 2021). "Western blot analyses from infigratinib‐resistant tumour collected at different passages indicated an elevation in cell cycle proteins such as cyclin E2, cyclin B1, Cdc25C, p‐Cdc2, cyclin D1, Rb and p‐Rb." (PMID 33179425, 2021). "While this is still a small number of patients, the data support that cyclin E2 expression is increased when the tumor develops resistance to fulvestrant and should be further studied as a biomarker of resistance to fulvestrant in the clinical setting." (PMID 33602273, 2021). "In the clinical tumor stage study, the worse prognosis of stage III and IV tumors was associated with higher expression of CCRGs (p<0.05, respectively), except for the CCNE2 gene." (PMID 33403032, 2021). "In NSCLC, miR-30d represses tumor cell proliferation and motility by directly targeting CCNE2 and NFIB." (PMID 34112238, 2021). "To assess the clinical relevance of our findings, we analyzed cyclin E2 expression in tumor samples collected from three patients treated with fulvestrant." (PMID 33602273, 2021). "Comparison of pre- and post-treatment paired tumor biopsies from patients treated with fulvestrant revealed an upregulation of cyclin E2 upon development of resistance." (PMID 33602273, 2021). "Meanwhile, the results of WB and immunohistochemistry showed that hsa_circ_0000073 silencing markedly reduced the expression of CCNE2 or MDM2 in tumor tissues." (PMID 34568326, 2021).
tumor (continued). "Upregulated CCNE2 in various cancers was shown to be correlated with tumorigenesis and tumor proliferation, invasion, and migration by affecting tumor cell viability and apoptosis." (PMID 33403032, 2021). "By H score analysis, the expression of both CARM1 and CCNE2 were profoundly elevated in the NSCLC tumor tissues when compared with that in the adjacent non-tumor tissues (n =20, **P < 0.01)." (PMID 32487779, 2020). "Eight miRNA-449-family target genes (CDC25A, SIRT1, GMNN, E2F1, E2F3, BCL2, CDK2, and CCNE2) were selected; all of them involved in tumor development, cell cycle, and apoptosis." (PMID 30926829, 2019). "Recently, hsa-miR-30d was found downregulated and it functions as a tumor suppressor by directly targeting the CCNE2 in NSCLC." (PMID 29849986, 2018). "This group contains positive regulators of cell cycle and DNA-damage responses (i.e. Cdk4, Ccne2, and Met), whose suppression bestows anti-tumor functions to miR-34 family miRNAs." (PMID 28241004, 2017). "We found that miR-664b-5p functioned as a tumour suppressor and had an important role in the sensitivity to chemotherapy by targeting CCNE2." (PMID 28176879, 2017). "The cyclin E2 level was much lower in tumor tissues overexpressing miR-26a and the PCNA expression followed a similar pattern." (PMID 24116110, 2013). "We also examined the protein levels of CCNE2 in NPC tissue sections by immunohistochemical staining to identify which cell type in the tumour mass express cyclin E2 protein." (PMID 19293812, 2009). "In particular, we identified genes with major roles in mitosis, such as CDC28 protein kinase regulatory subunit 2 (CKS2) and cyclin E2 (CCNE2), which have been reported as over-expressed in various types of tumours." (PMID 19809427, 2009). "Consistent with the immunohistochemistry in other studies, several cell cycle regulators (e.g., CDKN2A (p16), CCNA2, CCNB1, CCNE2) were expressed at significantly higher levels in the tumor epithelium of African-Americans than European-Americans." (PMID 19225562, 2009). "Our findings establish OSMR as a molecular linchpin connecting intrinsic tumor survival pathways (PI3K/CCNE2) with extrinsic immunosuppressive reprogramming (BMP5/TANs/CD8+T cells), providing a clinically actionable target to overcome treatment resistance in GC." (PMID 41653653, 2026). "Furthermore, CCNE1 and CCNE2 generally influence tumor development and progression through the regulation of RB phosphorylation." (PMID 40346052, 2025). "The overexpression of CCNE2 also contributes to tumor drug resistance." (PMID 39925738, 2025). "In addition, given the high structural and functional similarity between CCNE1 and CCNE2, both genes are essential for tumor cell proliferation." (PMID 40346052, 2025). "By increasing its expression, it may be possible to suppress key downstream targets involved in tumor progression, including pathways like PI3K/AKT and cyclin E2 (CCNE2), which are linked to increased cell proliferation, migration, and invasion." (PMID 40034306, 2025). "Indeed, MiR-664b-5p inhibited tumour growth compared with the control in tumour xenograft models, and CCNE2 expression was also inversely correlated with miR-664b-5p expression in 90 TNBC patient samples." (PMID 36831687, 2023). "Mechanistically, tumor‐associated signaling pathways were enriched in the NR1H4 overexpression group and si-NR1H4 could induce the downregulation of Cyclin E2 (CCNE2)." (PMID 36123627, 2022).
tumor (continued). "Our study indicated that NR1H4 might be a potential tumor biomarker and therapeutic target for ccRCC which could promote cancer cell proliferation, migration and invasion via regulating CCNE2." (PMID 36123627, 2022). "Like E2F1, CCNE2 was also involved in tumor invasion, proliferation, and migration." (PMID 34521301, 2021). "Conclusion: hsa_circ_0000073 functions as a tumor promoter in OS to increase malignant tumor behavior through sponging miR-1252-5p and regulating CCNE2 and MDM2 expression, which could be a novel target for OS therapy." (PMID 34568326, 2021). "Rescue experiments validated miR-1252-5p mimics, or CCNE2/MDM2 short hairpin RNA could reverse the hsa_circ_0000073 overexpressing-induced impairment of malignant tumor behavior." (PMID 34568326, 2021). "Collectively, the overexpression of CCNE2 in tumor may promote tumorigenesis and cancer progression through various mechanisms, including increased proliferation, migration and invasion abilities." (PMID 32487779, 2020). "In NSCLC cells, CCNE2 enhances tumor proliferation, invasion, and migration." (PMID 33614501, 2020). "In addition, in vivo studies indicated that miR-664b-5p inhibited tumour growth compared with the control in tumour xenograft models, and we also found that CCNE2 expression was inversely correlated with miR-664b-5p expression in 90 TNBC patient samples." (PMID 28176879, 2017). "Furthermore, the results of PCR and immunohistochemistry (IHC) displayed lower CCNE2 mRNA and protein levels in miR-664b-5p–overexpressing tumour xenografts." (PMID 28176879, 2017). "To explore whether CCNE2 down-regulation by miR-664b-5p was responsible for the tumour suppression of this miRNA, we performed gain-of-function and loss-of-function analyses." (PMID 28176879, 2017). "However, cyclin E2 displayed strong positive staining in the tumor cells (90/106) and duct epithelial cells of the adjacent benign pancreatic tissues (76/106; P = 0.024)." (PMID 24116110, 2013). "In addition, the cyclin E2 siRNA had a similar role as the miR-26a-mimic in inhibiting tumor cell proliferation." (PMID 24116110, 2013). "Due to the limited availability of antibodies suitable for immunohistochemistry, the expression of cyclin E2 has been examined only through mRNA expression in tumour samples, whereas there is a comprehensive array of literature on the expression of both cyclin E1 protein and mRNA in cancer samples." (PMID 20180967, 2010). "In addition we have shown that tumours expressing both POLQ and CCNE2 are associated with an extremely poor outcome." (PMID 20700469, 2010). "Therefore, the next step was to validate whether miR-664b-5p functioned as a tumour suppressor by regulating CCNE2." (PMID 28176879, 2017). "Among them, EGFR(7p11.2), TWIST1(7p21.2), RAC1(7p22), MTDH(8q22.1), CCNE2(8q22.1), TNFRSF11B(8q24) and GRB2(17q25) might be good candidates, as they are reportedly associated with invasiveness and metastasis of tumor cells." (PMID 23457519, 2013). "In addition to cyclin E2, the integrated analyses that we performed also identified several pathways and GO terms, in particular related to cell proliferation, that are enriched in all three tamoxifen resistant tumor sets." (PMID 21789246, 2011). "However, cyclin E2 modulation does not always lead to changes in cyclin E1 expression, for example in smooth muscle cells the cyclin E2 siRNA treatment leads to downregulation of cyclin E1, and cyclin E1 and E2 are co-expressed in other tissues, and in some tumours." (PMID 20180967, 2010). "Mechanistically, OSMR directly recruits PI3K, amplifying PI3K/AKT signaling to increase cyclin E2 (CCNE2) expression, thereby sustaining tumor cell survival under chemotherapy-induced stress." (PMID 41653653, 2026).
tumor (continued). "Jin and colleagues proved that SIRT3 suppresses HCC development by delactylating cyclin E2 (CCNE2), a lactylated substrate of SIRT3, thereby reducing its ability to promote tumor growth in HCC cells." (PMID 40720394, 2025). "Unexpectedly, the up-regulated miR-5100 target genes (CCNE2, E2F1, E2F2) had higher levels of expression in the tumor samples." (PMID 39590378, 2024). "Sequencing of the transformed clones revealed increased expression of several oncogenes (including CCNE2, CDC25A and CIP2A) and decreased expression of tumour suppressors providing a rationale for the observed cellular transformation." (PMID 39237765, 2024). "Results from our analysis also indicate that, among the thirty genes which are differentially expressed in OSCCs, seven of them (namely BRCA1, CCNE2, CDC25C, CDK1, CDK2, E2F1, and FANCD2) positively correlate with both tumor grade and HPV infection." (PMID 36768994, 2023). "MiR-664b-5p, by targeting CCNE2 (a G1-cyclin binding CDK2) protein expression, acts as a tumour suppressor and increases sensitivity to PARP inhibitors." (PMID 36831687, 2023). "Then RNA was extracted from tumor tissue, and qRT-PCR showed that the expression of NEAT1, IL-34, VEGFA, SPINK1, S100A14, and P4HA2 was downregulated and the expression of CCNE2 was upregulated in NEAT1 knockdown tumor tissue." (PMID 36213831, 2022). "In the further study, we found that co-treatment with baicalin and Akt activator SC79 significantly attenuated the decreased tumor size and upregulated the expression of p-Akt, p-mTOR, CDK4, and Cyclin E2, when compared with baicalin treatment alone." (PMID 33585556, 2020). "IHC revealed that positive rates of CCNE1, CCNE2, and KI67 were reduced in the xenografted tumor tissues upon the injection of Exo-miR-144 agomir compared with the injection of Exo-NC-agomir (p < 0.05)." (PMID 32102682, 2020). "In conclusion, miR-664b-5p functions as a tumour suppressor and has an important role in the regulation of PARP inhibitors to increase chemosensitivity by targeting CCNE2." (PMID 28176879, 2017). "A tumor suppressor miRNA, miR-34a-5p, targeted several critical cancer genes, including CDK6, CCND1, CCNE2, E2F3 in the cell cycle pathway and VEGFA in the angiogenesis pathway." (PMID 27329603, 2016). "It is notable that tumours that overexpress both POLQ and CCNE2 confer an extremely poor prognosis relative to the other groups (HR 3.26; 95% CI 1.88 to 5.66; p<0.001)." (PMID 20700469, 2010). "Thus, PDCD11 upregulates C‐MYC protein but not C‐MYC mRNA to activate downstream effector molecules including but not limited to E2F1, CCNE2, and SKP2, thereby exerting its tumor‐promoting functions." (PMID 40051297, 2025). "Similarly, tumor tissues exhibited higher FBXO44 and Cyclin E2 protein expression and lower FOXP1 protein expression compared to adjacent normal tissues." (PMID 41051444, 2025). "Moreover, the dysregulation of cell-cycle-regulated genes (PLK1, CCNB1, CDKN2A, CCNE2, E2F1, and E2F2) by miR-5100 consistently resulted in upregulation in tumor tissues." (PMID 39590378, 2024). "In a recent whole-exome sequencing (WES) study, alterations in numerous genes including AKT1 and ERBB2, RAS pathway activating alterations, AURKA and CCNE2 amplification, and FGFR2 alterations were identified in tumor biopsies from patients with intrinsic or acquired CDK4/6i resistance." (PMID 37475004, 2023). "Additionally, it was found that BMMSC-derived exosomal miR-144 suppressed growth of tumor cells and colony formation in NSCLC by targeting CCNE1 and CCNE2." (PMID 33658392, 2021). "In addition, CCNE1, CCNE2, CCNB2, CCNA2, and CDK1 genes were highly expressed in fetal tumor tissues." (PMID 34395530, 2021).
tumor (continued). "Previous reports also showed that CCNE2 could drive tumour cell proliferation by activating its kinase partner CDK2,47, 48 but whether CCNE2 could directly regulate CDK4 was still unclear or CCNE2 affect the expression of CDK4 via an indirect manner." (PMID 32141702, 2020). "In addition, CCNE2 was the target of miR-3607-3p and miR-30d-5p in NSCLC to inhibit tumor cell proliferation and metastasis." (PMID 32596300, 2020). "Both CCNE2 and CDK2 expression remained high and unchanged after doxorubicin treatment, and it has been described that overexpression and interaction of these two genes is related with tamoxifen-resistance mechanisms in breast cancer." (PMID 30926829, 2019). "MP-HX downregulated the expression of genes that could promote anti-apoptotic effect, cell cycle progression, tumor development and progression, which include BIRC5, CCNA2, CCNB1, CCNB2, CCNE2, CDK1/2/6, GINS2, HELLS, MCM2/10 PLK1, RRM2 and SKP2." (PMID 30042885, 2018). "We found that CCNA2, CCNE2 and CDC25A are significantly up-regulated in PTHLH expression Ca9-22 cells and those are also up-regulated in the in Taiwanese (p < 0.01) and TCGA data (p < 0.001) HNSCC tumor." (PMID 28120940, 2017). "KEGG pathway enrichment analysis showed that CCNE2, MYC, CREB3L4, and NKD2 are involved in many tumor-related pathways, suggesting that these genes may play an essential role in cancer development." (PMID 28056099, 2017). "One of the potential mechanisms that underline the DNMT3B-mediated arrest involves the ability of DNMT3B siRNA to reduce the expression of different cyclins (Cyclin B1, Cyclin D1 and Cyclin E2) and to block the pRB/E2F1 pathway by inducing de-phosphorylation of RB tumour suppressor." (PMID 27764816, 2016). "The amplified genes with overexpression in each tumor sample groups might be the potential therapeutic targets for the specific tumor type, such as CCND1, CCNE2 for the ER group and E2F5, EIF2C2 for the PR group." (PMID 26273658, 2015). "Our results reveal a novel mechanism by which hERG1 activation impacts the tumor marker cyclin E2 that is independent of cyclin E1, and suggest a potential therapeutic use for hERG1 channel activators." (PMID 25596745, 2015). "It is also interesting to note that, unlike cyclin E1 and Ki67 which are expressed in most proliferating normal and tumor cells, cyclin E2 levels are often low to undetectable in non-transformed cells and increased significantly in tumor-derived cells." (PMID 25475054, 2014). "Strong positive cyclin E2 staining was detected in tumour cells, but not in paired normal nasopharyngeal epithelium." (PMID 19293812, 2009). "In the yellow cluster, cell cycle regulators such as CCNE2, MYBL2, and MCM4 were strongly suppressed in the combination, confirming that this approach induced cell cycle arrest and exerted a stronger inhibition of tumor cell proliferation compared to either treatment alone." (PMID 40753072, 2025). "Using the other markers (SLC6A8, HJURP, CCNE2), the detection of the spiked-in tumor cells was not possible due to high background signal from PBMCs and the low expression in the selected three cell lines, which results in equal Ct values in spiked and unspiked samples." (PMID 36831613, 2023). "Ccne2 expression was not significantly regulated in tumours and livers of all cohorts." (PMID 34830835, 2021). "Unlike CARM1, CCNE2 was preferentially in the nuclei of tumor cells." (PMID 32487779, 2020). "Analysis of tumor lysates from control and metformin-treated mice showed an obvious increase in expression of phosphorylated AMPKa proteins; and there was a significant decrease in Yap1, CCNE1 and CCNE2 protein levels in tumors from mice treated with metformin." (PMID 31455378, 2019). "Therefore data from clinical HNSCC patients also demonstrate that PTHLH might regulate tumor growth through cell cycle regulators, namely, CCNA2, CCNE2, and CDC25A." (PMID 28120940, 2017).